CRP (C-reactive protein)
Diseases named in the same sentence as CRP in open-access papers (continued):
Sharing a sentence is not in itself a finding about the gene and the disease.
Obesity (continued). "Furthermore, significantly higher circulating insulin levels, hs-CRP, and HbA1C, as well as HOMA-IR values, were observed in women with obesity Also, the obese group showed higher levels of creatinine, TC, and LDL-C compared to the normal-weight controls." (PMID 36609306, 2023). "Moreover, CRP and ESR are inflammatory markers, levels of which are increased under metabolic abnormalities such as obesity and related metabolic syndromes." (PMID 36771387, 2023). "In the class 3 obesity group, we found positive correlations between leukocytes and VF and CRP and between granulocytes and CRP, and a negative correlation between CD8+CD45RA+CD45RO+ T lymphocytes and VF." (PMID 37334132, 2023). "In a previous meta-analysis of inflammatory markers in PCOS patients, circulating C-reactive protein (CRP) was significantly elevated independent of obesity, leading to a chronic inflammatory condition." (PMID 36609436, 2023). "Significant predictors for severe disease (classes III and IV) according to the WHO clinical classification scale included high LDH, CRP, age, AEP, and NLR, and comorbidities, including cardiovascular diseases, lung diseases, and obesity, and the presence of two or more comorbidities." (PMID 37766326, 2023). "A meta-analysis has also revealed a positive correlation between obesity markers (such as HOMA-IR, BMI, body AT percentage, waist circumference, and WHR values, as well as triglycerides, total cholesterol, and CRP concentration) and chemerin levels in patients with obesity or MetS." (PMID 38136166, 2023). "Previously, it has been identified that elevated CRP concentrations are comparable for individuals with metabolically unhealthy obesity and non-obesity." (PMID 37841401, 2023). "Another meta-analysis of 20 RCTs showed that flaxseed and its derivatives did not change circulating C-reactive protein (CRP) despite populations with obesity." (PMID 37778442, 2023). "Furthermore, patients with MS and obesity have shown low levels of TAS and high levels of serum C-reactive protein (CRP), indicating low-grade systemic inflammation." (PMID 38203362, 2023). "Obesity-related low-grade inflammation did not come to light in the periphery, as plasma CRP in WKY HF saline was not higher, compared to WKY LF saline rats." (PMID 36678151, 2023). "Serum leptin, resistin, PAI-1, and CRP levels differed significantly between children with normal body weight and those with overweight/obesity, and between those with and without MetS (all p<0.05), being higher in children with overweight/obesity and MetS." (PMID 36920931, 2023). "Moreover, it has been demonstrated that ATF3 genotypes/haplotypes cooperate with obesity to set the levels of C-reactive protein (CRP), which is an acute-phase protein correlated with poor prognosis in various types of cancer and obesity state." (PMID 37447165, 2023). "Obesity is also a disease characterized by the presence of low-grade chronic inflammation, and the recovery of normal IGF-1 synthesis over time after BS was reported to be independently related with CRP." (PMID 36904198, 2023). "The inflammatory nature of obesity could enhance the activity of lactate dehydrogenase (LDH), CRP, and plasminogen activator inhibitor 1 (PAI-1)." (PMID 37237937, 2023). "Similar to the findings of our study, previous authors have demonstrated excellent health outcomes for individuals with obesity or MetS undergoing RYGB including a remission of comorbidities, reduction in systemic inflammation, and significant reduction in high CRP levels." (PMID 37571250, 2023). "A research explained that elevated levels of CRP were found in women with PCOS irrespective of their obesity condition." (PMID 36677054, 2023). "C-reactive protein (CRP) was greatly elevated in basal plasma (10.5 ± 6.2 mg/l) versus controls (0.9 ± 0.3 mg/l), indicating systemic inflammation characteristic of severe obesity." (PMID 37777014, 2023).
Obesity (continued). "Baseline results of pro-inflammatory biomarkers, including serum interleukin (IL)-6, serum and gingival crevicular fluid (GCF), tumor necrosis factor (TNF)-a, serum C-reactive protein (CRP)/hs-CRP, and serum and GCF resistin, were higher in obesity subjects than in normal weight subjects." (PMID 37798684, 2023). "Similarly, systolic blood pressure (SBP), diastolic blood pressure (DBP), and C-reactive protein (CRP) were higher among the NAFLD and obesity group patients (p<0.05)." (PMID 37927726, 2023). "Increased adipose tissue inflammation in CKD patients is independent of obesity status but at the same time obesity-associated changes in fat mass in CKD patients also correlate with CRP levels and soluble CD163 levels, which is an activated macrophage marker." (PMID 37128293, 2023). "In the general population, CRP and BMI levels are positively correlated for both sexes regardless of race and ethnicity, consistent with obesity creating a pro-inflammatory state." (PMID 38003780, 2023). "Our subsample with overweight/obesity showed significant differences on various inflammatory markers, and those with abdominal obesity had higher CRP levels compared with those without." (PMID 36920931, 2023). "A paired t-test of phenotypic measurements indicates that many traits are significantly different between the lower and higher BMI groups of siblings, including C-reactive protein (CRP), which is a measure of systemic inflammation, important comorbidity of obesity." (PMID 37452040, 2023). "In comparison to the laboratory test results, the pre-operative white blood cell (WBC) count and CRP were found to be significantly different in the obesity group compared to the non-obesity group." (PMID 37679736, 2023). "Despite this, there was no apparent reduction in systemic inflammation in either obesity or non-obese patients as measured by serum levels of CRP/hs-CRP at the 3-month follow-up." (PMID 37798684, 2023). "Compared with non-obese patients, patients with obesity had higher tender joint counts, enthesitis scores and CRP, but not swollen joint counts." (PMID 37709527, 2023). "In the NHANES, although the overall correlations between 25(OH)D and CRP were weak and negative, there were non-significant negative correlations in the obesity group but positive significant correlations in the normal BMI group." (PMID 36789936, 2023). "In our study, 13.4% of participants with BMI ≥ 30 kg/m2 had CRP ≤ 1 mg/L, which further highlights that inflammation initiation is not necessarily a consequence or a correlate of obesity." (PMID 36030344, 2022). "The adjustment for potential confounding factors, including age, male sex, smoking, drinking, education, physical activity, obesity, hypertension, dyslipidemia, and CRP levels in models 1 and 2, did not change this relationship." (PMID 36057713, 2022). "In three different studies without any obesity distinction, hs-CRP was significantly higher in PCOS similar to our results." (PMID 35657129, 2022). "In another study, levels of high sensitivity-CRP were higher in 12-year-old children exposed to maternal obesity during pregnancy compared to not exposed." (PMID 35360231, 2022). "CRP is a direct measure of inflammation while ESR is an indirect measure and can be affected by conditions or factors unrelated to acute or chronic inflammation like increased age, female sex, anemia, end-stage renal disease and obesity." (PMID 36381804, 2022). "In people with overweight/obesity, once-weekly semaglutide 2.4 mg and 1.0 mg reduced CRP concentration irrespective of baseline BMI/bodyweight/glycaemic status compared with placebo." (PMID 36467859, 2022). "We determined the impact of HFD-induced obesity, combined or not with polyphenols on leptinemia, adiponectinemia and plasma CRP levels in mice." (PMID 35624723, 2022).
Obesity (continued). "Indeed, a study of metabolic syndrome in middle-aged and older adults in Taiwan showed that PBF, obesity, hip circumference, waist circumference, and waist-to-hip ratio had a significant positive correlation with NLR and C-reactive protein levels." (PMID 35764967, 2022). "The direct effect of obesity on poor PF (i.e., not operating via CRP), was 1.97 (95% CI: 1.51, 2.56), with an indirect effect of 1.23 (95% CI: 1.10, 1.37)." (PMID 35301057, 2022). "From our perspective, the inflammatory nature of obesity could contribute to developing the symptoms of IBS through the stimulation and release of proteins as complement components and CRP." (PMID 36558394, 2022). "Subclinical inflammation is one of the important facets of PCOS, with and without obesity, which manifests by elevated counts of white blood cells (WBCs), interleukin (IL)-6, and C-reactive protein (CRP) levels." (PMID 35454373, 2022). "A systematic review with a meta-analysis of subjects with overweight or obesity reported that supplementation with vitamin D did not decrease CRP, TNF-α, or IL-6 levels." (PMID 35893929, 2022). "It has been observed that pregnant women with obesity have a more pronounced increase in CRP concentrations during gestation than pregnant women with normal weight." (PMID 35270396, 2022). "Individuals with obesity and depression evidence increased concentrations of peripheral and central inflammatory cytokines and acute phase reactants, such as interleukin (IL)-6, tumor necrosis factor alpha (TNF-α), and C-reactive protein (CRP) ⁠⁠." (PMID 35287577, 2022). "For example, in individuals with obesity (compared to those without obesity), CRP values were 81.06% (95% CI: 70.40%, 91.72%) higher and odds of poor PF were 2.46 (95% CI: 2.01, 3.01) times greater." (PMID 35301057, 2022). "Our results showed no significant group differences in terms of gender, age, risk factors such as cardiovascular and neurological diseases, type 2 diabetes, and obesity (p > 0.05), or in pre-treatment inflammatory status, evaluated by white blood cell (WBC) count and C-reactive protein (CRP) levels." (PMID 36672518, 2022). "Obesity, per se, is known to be a chronic inflammatory state and C-reactive protein (CRP) is elevated in non-obese adult offspring of two obese parents." (PMID 35360231, 2022). "This age range is still young enough that increases in CRP would likely reflect effects of inflammatory conditions such as overweight/obesity as opposed to independent age effects." (PMID 35035976, 2022). "For WC-based obesity, the probability of MHO was the highest, in which it increased, plateaued at about 10 μg/mL, then decreased gradually following a unit increase in the hs-CRP value." (PMID 35267891, 2022). "Nonetheless, there remains a substantial effect of obesity on PF operating via pathways that do not include CRP that need to be considered." (PMID 35301057, 2022). "In fact, independent of obesity, elevated levels of proinflammatory factors, including C-reactive protein (CRP), fibrinogen, tumor necrosis factor-α and interleukin-6, have been reported among patients with OSA10." (PMID 35273744, 2022). "The direct effect of obesity on poor PF (i.e., not operating via CRP), expressed as an OR, was 1.97 (95% CI: 1.51, 2.56); the indirect effect, via CRP, was 1.23 (95% CI: 1.10, 1.37)." (PMID 35301057, 2022). "In conclusion, treatment with once-weekly s.c. semaglutide 2.4 mg compared with placebo led to substantial reductions in body weight and reduced CRP concentration in people with overweight or obesity, with or without type 2 diabetes." (PMID 36467859, 2022). "In the STEP 1, 2, and 3 trials in adults with overweight or obesity, with and without type 2 diabetes, treatment with semaglutide 2.4 mg resulted in significant reductions in CRP concentrations compared with placebo, irrespective of BMI or baseline bodyweight." (PMID 36467859, 2022).
Obesity (continued). "Additionally, we also observed that overweight and obesity among ALL survivors were positively correlated with the levels of Apo-C3, apolipoprotein H (Apo-H), Apo-J, and CRP (Apo-C3: r = 0.60; Apo-H: r = 0.49; Apo-J: r = 0.41; CRP: r = 0.47; p < 0.05; )." (PMID 36142534, 2022). "The major risk factors are structural heart disease, LAd, incomplete pulmonary vein (PV) isolation, low LA voltage, C-reactive protein, AF duration, obesity, non-PV triggers, and NT-proBNP." (PMID 36386356, 2022). "This study examined the mediational influence of BMI and hip and waist circumferences (as markers of obesity/increased adiposity or its redistribution) influencing the LLS and serum CRP levels (as an inflammatory marker) in middle-aged and older African Americans." (PMID 35629167, 2022). "A moderate increase in circulating C-reactive protein (CRP) level was also detected in patients with PCOS with or without obesity; this finding indicates that patients with PCOS develop low-grade chronic inflammation." (PMID 36551953, 2022). "Some researches showed that CRP was correlated with obesity and the role of obesity in inflammation can not be ignored." (PMID 35996695, 2022). "In obesity, hypertrophy of adipocyte cells promotes the production of pro-inflammatory factors such as TNF-α, monocyte chemoattractant protein-1 (MCP-1), IL-6, endothelial adhesion molecules, C-reactive protein (CRP) and chemotactic mediators." (PMID 35162142, 2022). "In addition, WHR has been previously reported to be associated with inflammation markers, such as high-sensitivity C-reactive protein, TNF-α, amyloid A, and interleukine-6, in children affected by obesity-driven inflammation." (PMID 35806923, 2022). "BMI of participants was either matched on selection (79 studies) or adjusted for during statistical analysis (six studies) concluding that the difference in CRP was attributed to PCOS status rather than obesity." (PMID 33800490, 2021). "Elevated CRP correlates with interleukin (IL)–6, tumor necrosis factor (TNF)–α, obesity or insulin resistance, which may indicate a link between chronic inflammation and endothelial dysfunction." (PMID 33806236, 2021). "Although average salivary CRP levels were higher in participants with obesity, this was not statistically significant due to large variations across both cohorts." (PMID 34158611, 2021). "Chronic inflammation, marked by raised serum interleukin 6 (IL-6), C-reactive protein (CRP) and tumor necrosis factor alpha (TNF-α), anemia and lower hematocrit levels, immune activation, as well as obesity and other comorbidities have also been defined as etiologies of frailty." (PMID 34574503, 2021). "Remarkably, the reduced expression was found in particular for CRP and CD36 (respectively) genes in PGW of the DS group compared to the DIO rats, suggesting that seed supplementation can reduce the inflammatory status induced by obesity." (PMID 33807712, 2021). "Though similarly affected by the obesity burden, there is no explanation for a common mechanism behind the shift in these distributions for CRP and teeth as the mean age difference was merely odd 6 years." (PMID 32827080, 2021). "TRT interruption reduced TT to hypogonadal levels in Group A and resulted in worsening of obesity parameters, AMS, IPSS, residual voiding volume and bladder wall thickness, IIEF-EF, and PSA, while CRP and prostate volume were unchanged until treatment resumed whereby these effects were reversed." (PMID 34552788, 2021). "The immune dysregulations include increased levels of inflammatory markers such as C - reactive protein (CRP), interlukin-6 (IL-6), tumour necrosis factor alpha (TNF alpha), and other cytokines indicating insulin and leptin resistance, obesity, inflammation, and higher rates of metabolic syndrome." (PMID 34895175, 2021). "In PCOS, increases in NFκB activation and circulating CRP and decreases in IκBα protein following saturated fat ingestion are independent of obesity." (PMID 34239559, 2021).
Obesity (continued). "Using the Léger's and LM-LBM equations, the prevalence of central obesity, general overweight/obesity, elevated BP, low HDL-C, elevated atherogenic index, and CRP > 3 mg/L was significantly higher in males at the upper tail of eGFR distribution vs. the lower tail." (PMID 34778125, 2021). "PCOS is a low-grade inflammatory state; women with PCOS have higher levels of inflammatory markers such as C reactive protein (CRP), tumor necrosis factor α (TNF-α), and interleukin 6 (IL6), independent of associated obesity." (PMID 33746952, 2021). "Obesity, immunosuppression, gender, CRP levels were not related to recurrence rate in the two main groups (p > 0.05)." (PMID 35056340, 2021). "It has been reported that individuals with obesity have higher concentrations of MCP-1 when compared to non-obese controls, with a positive association of MCP-1 with CRP and IL-6, and a negative association with HDL-C." (PMID 34822430, 2021). "Similarly, in our previous study, we did not observe the significant differences between serum levels of CRP, TNF-α, IL-1, and IL-6 of girls with PCOS and normal weight compared to the group with overweight and obesity." (PMID 33849511, 2021). "The following parameters/characteristics were comparably distributed between subjects with and those without recovery (always recovery vs. no recovery): gender, AKI onset, initial CRP, vasopressor therapy, invasive ventilation, obesity, and neoplasia." (PMID 33986959, 2021). "IL-6 can induce expression of C reactive protein (CRP), which are together used as clinical markers of inflammation and risk of T2DM development, independent of obesity." (PMID 33670215, 2021). "Blood HDL cholesterol concentration was lower (p < 0.05), whereas blood uric acid, CRP, LDL cholesterol, triglycerides, triglyceride-to-HDL cholesterol ratio, glucose, insulin, and leptin concentrations were all higher (p < 0.05) in adolescents with obesity." (PMID 34682324, 2021). "Moreover, studies also showed that patients with obesity who lost their weight had lower systolic blood pressure, HbA1c, low-density lipoprotein (LDL), triglycerides and CRP, and a higher high-density lipoprotein (HDL)." (PMID 34684569, 2021). "Consistent with this assumption, patients with PCOS exhibit low-grade inflammation, characterized by elevated levels of CRP and independent of obesity." (PMID 33746952, 2021). "Obesity-associated chronic low-grade inflammation characterized by high levels of plasmatic inflammatory markers [C-reactive protein, interleukin 6 (IL6) or tumor necrosis factor α (TNFα)] largely contributes to the development of the obesity-related chronic metabolic diseases." (PMID 35024040, 2021). "Our findings are in agreement with the literature, since patients with higher degrees of obesity and lower levels of VITD present a pro-inflammatory profile exacerbated with CRP levels and, in addition to lipid profile and HOMA-IR, show a superior metabolic risk and persistent immune activation." (PMID 34578857, 2021). "Indeed, circulating levels of several inflammatory cytokines (i.e., CRP, IL‐1β, IL‐6, IL‐8, MCP‐1, and TNFα) have been shown to be increased in obesity." (PMID 34110720, 2021). "However, there are no published data on the neutrophil-to-lymphocyte ratio (NLR), lymphocyte-to-monocyte ratio (LMR), leukocytes, CRP, nutritional interventions with EVOO and a healthy dietary pattern in individuals with severe obesity." (PMID 34836393, 2021). "Obesity is a chronic low-grade inflammatory condition that stimulates inflammatory cytokine release, such as tumor necrosis factor (TNF-α), interleukin-6 (IL-6), and C-reactive protein (CRP)." (PMID 34258058, 2021). "Indeed, AMY1 was significantly decreased and the obesity-related salivary biomarkers resistin, MCP-1, TNF-α, IL-6 and CRP were significantly increased in overweight/obese children compared with normal weight children." (PMID 34444230, 2021).